GRK2 (G protein-coupled receptor kinase 2)
Diseases named in the same sentence as GRK2 in open-access papers (continued):
Sharing a sentence is not in itself a finding about the gene and the disease.
heart failure (continued). "In line with this, our data also indicate that levels of GRK2 are highly upregulated in myocardium of patients with cardiac failure." (PMID 30024944, 2018). "Nevertheless, the GRK2-inhibitory activity of RKIP was insufficient to protect against RKIP-induced heart failure." (PMID 30687708, 2018). "A mounting body of evidence indicates that GRK2 expression and activity are elevated in lymphocytes from hypertensive and heart failure patients." (PMID 30061705, 2018). "Experimental evidence indicates that a major cardio-protective mechanism induced by GRK2 inhibition relies on re-sensitization of desensitized beta-adrenoceptors in heart failure." (PMID 30687708, 2018). "Our results indicate that although the use of GRK2 inhibitors for treatment of heart failure is promising; the benefits must be outweighed against their potentially deleterious effects on the kidney function." (PMID 30061705, 2018). "On the other hand, there are multiple lines of evidence, which show that inhibition of exaggerated GRK2 activity in experimental models of heart failure is cardio-protective." (PMID 30687708, 2018). "Human studies detected an increase GRK2 protein expression in lymphocytes from hypertensive and heart failure patients presumably due to the desensitization of β adrenergic receptors (βARs) that mediate vasodilatation." (PMID 30061705, 2018). "In murine hearts in vivo, the MR has been documented to promote heart failure by activating GRK2-dependent cardiac apoptosis and GRK5 nuclear accumulation-dependent cardiac hypertrophy." (PMID 30486399, 2018). "Inhibition of the G-protein-coupled receptor kinase 2 (GRK2) is an emerging treatment approach for heart failure." (PMID 30687708, 2018). "Inhibition of GRK2 improved cardiac function and survival and diminished cardiac remodeling in various animal heart failure models." (PMID 28759639, 2017). "Changes in β-AR density, cAMP production, and GRK2 expression occurs in both right and left heart failure." (PMID 29232706, 2017). "We also show human data consistent with MR activation status in heart failure influencing GRK2 levels." (PMID 26932512, 2016). "The expression of GRK2 is essential for cardiac development, as GRK2−/− mice die before E16.0 due to heart failure." (PMID 29367572, 2016). "Since the discovery of a linkage between GRKs and cardiovascular disease including hypertension and heart failure, GRKs—especially GRK2 and GRK4—have been considered pharmaceutical targets for the treatment of cardiovascular disease." (PMID 27390269, 2016). "In contrast, it was revealed that overexpression of GRK2ct (also known as β-ARKct), a peptide inhibitor composed of the last 194 amino acids of GRK2, was successful for the prevention of heart failure through the inhibition of mitochondrial translocation." (PMID 24597858, 2014). "We tested the effects of cardiac-targeted GRK2 inhibition in vivo exclusively on β2AR signaling under normal conditions and in heart failure (HF)." (PMID 23984976, 2013). "Blocking the interaction of GRK2 with PI3K improves contractile function during heart failure by reversing βAR desensitization abnormalities and restoring βAR signaling." (PMID 24265619, 2013). "Studies from our lab have shown that decreasing myocardial G protein–coupled receptor kinase 2 (GRK2) activity and expression can prevent heart failure progression after myocardial infarction." (PMID 23805205, 2013). "Because the expression and activity of GRK2 are increased in multiple animal models of heart disease and in human heart failure, it has been suggested that enhanced GRK2 activity can explain the concomitantly decreased receptor responsiveness." (PMID 21283592, 2011). "Our findings are in line with previous reports that abnormal up-regulation of GRK2 can chronically and constantly activate β1-adrenergic receptor (β1AR) and accelerate heart failure development." (PMID 21283592, 2011).
heart failure (continued). "Several lines of evidence implicate GRK and beta-arrestin expression in AD and after cerebral hypoxia/ischemia (HI) and the differential GRK2 expression in compensated hypertrophy and heart failure after myocardial infarction in the rat." (PMID 20204079, 2009). "Further, elevated levels of GRK2 mRNA and GRK2 activity have been reported in human left ventricle explants from heart failure patients." (PMID 20204079, 2009). "Increased GRK2 in heart failure (HF) initially may be protective but ultimately leads to maladaptive effects such as GPCR desensitization, insulin resistance, and apoptosis." (PMID 39960030, 2025). "Notably, while GRK2 inhibition seems to be a therapeutic approach to heart failure, its precise role in mitochondrial dynamics and pathology needs further investigation." (PMID 40076919, 2025). "However, GRK2 inhibition increases β-adrenergic receptor-dependent cardiomyocyte and cardiac contractility and reverses cardiac dysfunction in heart failure models." (PMID 38961282, 2024). "Accordingly, our research exposed sympathetic overactivity in companies with down-regulated GRK2 expression may play critical roles in AF initiation and perpetuation in chronic partial SD-induced heart failure and AF." (PMID 39062858, 2024). "Importantly, GRK2 expression is upregulated in heart failure and GRK2 inhibition improves cardiac remodeling." (PMID 37283586, 2023). "Also, the inhibition of G-protein-coupled receptor kinase 2 (GRK2) showed to play an important beneficial role in cardiac mitochondrial metabolism in a heart failure setting." (PMID 37914850, 2023). "Thus, the damage as a dominant version is located between the receptor and G protein and the importance of GRK2 in heart failure is indicated, explaining the increased activity observed in it." (PMID 37189604, 2023). "GRK2 augmentation has been reported in cardiovascular diseases such as hypertension, myocardial infarction, and heart failure, suggesting that GRK2 inhibition may have cardioprotective effects." (PMID 38139099, 2023). "The expression of MIF and GRK2 was significantly upregulated in H9C2 cardiomyocytes as a function of glucose concentration, and GRK2-mediated increases in MIF levels were linked to cardiac insufficiency in diabetic patients." (PMID 36871006, 2023). "All these angiotensin system inhibitors are prognosis-improving therapies of heart failure and could counteract GRK2 inhibition-induced weight gain, which is mediated by AGTR1 sensitisation." (PMID 35203304, 2022). "GRK2 inhibition by βARKct is successful in vivo and could improve the disease symptoms of heart failure in numerous experimental cardiovascular disease models of mouse, rat, rabbit and porcine origins." (PMID 35203304, 2022). "Therefore, the net effect of the dual RAF1 and GRK2 inhibition by RKIP in vivo is a detrimental cardiac phenotype, which predisposes to cardiac fibrosis, cardiac dilation and heart failure." (PMID 35203304, 2022). "Despite the fact that the majority of the studies have focused on the reduced β-adrenergic responsiveness as a consequence of increased GRK2 expression in cardiac hypertrophy and heart failure, there are a number of studies showing decreased expression of GRK2 in the ischemic myocardium." (PMID 36430599, 2022). "Inhibiting GRK2 can enhance cardiac contractility and protect from adverse heart remodelling in disorders related to cardiac dysfunction, suggesting its inhibition as a therapeutic strategy for heart failure." (PMID 36357925, 2022). "Moreover, by this mechanism, GRK2 inhibitors are expected to counteract symptoms of cardiac cachexia as a potentially life-threatening condition in severe heart failure." (PMID 35203304, 2022). "GRK2 is upregulated in failing hearts of patients with heart failure." (PMID 35203304, 2022). "GRK2 inhibition is an emerging treatment approach of heart failure." (PMID 35203304, 2022).
heart failure (continued). "RKIP induces heart failure by its dual functions as a GRK2 inhibitor and RAF1 inhibitor." (PMID 35203304, 2022). "RKIP-mediated cardiotoxic effects could further be aggravated by GRK2-inhibition-mediated sensitisation of heart failure-promoting GPCRs coupled to Gq/11 and Gs proteins." (PMID 35203304, 2022). "Likewise, therapy with a cardioprotective GRK2 inhibitor, such as the βARKct, lowered the pathologically elevated Grk2 levels of heart failure rats." (PMID 35203304, 2022). "The reduced model is used to predict how the dynamics of intracellular cAMP depend on the concentrations of norepinephrine (NE), phosphodiesterases 3 and 4 (PDE3,4), G-protein coupled receptor kinase 2 (GRK2), and β1-AR, in healthy conditions and a simple model of early stages of heart failure." (PMID 33740423, 2021). "As one example, myocardial GRK2 levels strongly correlate with GRK2 levels in peripheral blood lymphocytes, and GRK2 levels in peripheral blood lymphocytes are significantly higher in patients with myocardial infarction and heart failure (HF)." (PMID 33546162, 2021). "Among the many structural and physiological changes in heart failure, up-regulation of GRK2 is frequently observed and suspected to play a role in cardiac pathology, whether due to its effects on adrenergic signaling or other interactions." (PMID 33740423, 2021). "In this review, we will discuss the metabolic role of GRK2 in those conditions that are characterized by insulin resistance (diabetes, hypertension, heart failure), and the potentiality of its inhibition as a therapeutic strategy to revert both insulin resistance and its associated phenotypes." (PMID 33467677, 2021). "Our results suggest that a simplified two-dimensional model can capture the extent to which the isolated adrenergic signaling pathway mediates both the potentially harmful effects of GRK2 in heart failure and the therapeutic benefits of its downregulation by pharmaceutical agents." (PMID 33740423, 2021). "GRK2 is a key regulator of cardiovascular physiopathology, and changes in the GRK2 levels in the heart have been reported in different pathological situations, including heart failure, hypertension, and lipid overload." (PMID 33803070, 2021). "Notably, the MR was recently shown to promote heart failure by activating GRK2-dependent apoptosis and GRK5 nuclear accumulation-dependent hypertrophy in transgenic mouse hearts in vivo." (PMID 32326036, 2020). "When GRK2 ability to suppress β-adrenergic signaling is reduced by overexpression of GRK2 C-terminus that outcompetes endogenous full-length kinase for the G protein βγ-subunit, which targets GRK2 to the plasma membrane where β-adrenergic receptors reside, heart failure is alleviated." (PMID 30837883, 2019). "Therefore, situations of neurohumoral activation and of obesity/insulin-resistance converge in promoting cardiac GRK2 upregulation, which emerges as a potential factor linking insulin-resistant pathological conditions and heart failure." (PMID 30837878, 2019). "The GRK2 signaling hub is important in signaling pathways and processes related to very relevant cardiovascular pathological conditions (heart failure, cardiac hypertrophy, hypertension) and to diseases related to altered metabolic homeostasis (obesity metabolic syndrome, type 2 diabetes, NAFLD)." (PMID 30837878, 2019). "Hence, the desensitization of β-AR by inhibition of GRK2 is considered as a potential route for heart failure treatment." (PMID 31506468, 2019). "On the other hand, adenoviral-mediated delivery of the C-terminal region of GRK2 (βARKct) also has a protective effect in heart failure and acute myocardial infarction settings in murine and pig models by mechanisms likely involving prevention of the activation of GRK2 by Gβγ subunits." (PMID 30837878, 2019). "This study may be used in designing more potent and selective GRK2 inhibitors for therapeutic intervention of heart failure." (PMID 31506468, 2019).
heart failure (continued). "Hence, the inhibition of GRK2 is considered to be an important drug target for the treatment of heart failure." (PMID 31506468, 2019). "Based on these data, inhibition of GRK2 appears as a promising treatment approach of heart failure." (PMID 30687708, 2018). "Signs of heart failure developed in RKIP-transgenic mice despite of significant GRK2 inhibition." (PMID 30687708, 2018). "We asked whether GRK2-K220R was cardio-protective in a model of heart failure induced by chronic pressure overload imposed by abdominal aortic constriction, AAC." (PMID 30687708, 2018). "Thus, sensitization of the heart failure-promoting AT1 receptor by the RKIP-GRK2 interaction contributes to heart failure whereas dominant-negative GRK2-K220R is cardioprotective." (PMID 30687708, 2018). "GRK2 expression increases in different cardiac hypertrophy and heart failure human conditions." (PMID 27832814, 2016). "As an upregulation of GRK2 in cardiomyocytes precedes the development of heart failure, this finding might suggest that MIF could promote heart failure by amplifying GRK2 expression." (PMID 26347749, 2015). "An upregulation of GRK2 in nonmyocyte cardiac cells is linked to enhanced β1-adrenergic receptor signalling and is associated with heart failure." (PMID 23690662, 2013). "A critical role for GRK2 in heart disorders is supported by multiple lines of evidence; cardiac GRK2 levels increase in human and experimental models of HF, ischemia, hypertension, and the early phases of maladaptive myocardial remodeling and lymphocytes of patients with cardiac failure." (PMID 40076919, 2025). "The crosstalk between GRK2 and mitochondrial dynamics, including oxidative phosphorylation, ROS production, and apoptosis, highlights its potential impact on cardiovascular disease, particularly in heart failure, ischemic damage, and other cardiac dysfunctions." (PMID 40076919, 2025). "Upregulation of Grk2 is induced by long-term stimulation of β-adrenoceptors and could reflect overstimulation of the sympathetic nervous system, which is characteristic of heart failure." (PMID 35203304, 2022). "Thus, compounds with hydrazone cores express inhibitory effects against numerous enzymes, such as cyclooxygenase (COX-1 and COX-2), acetyl- and butyrylcholinesterase (AChE and BuChE), monoamine oxidase A (MAO A), as well as G-Protein-Coupled Receptor Kinase 2 (GRK2) involved in heart failure." (PMID 35706666, 2022). "Separately, recent work has identified a wide range of targets of GRK2 and demonstrated that reduction of GRK2 activity, either genetic or pharmacologic, may improve overall cardiovascular function, particularly in heart failure." (PMID 33740423, 2021). "In contrast to the “heart failure” conditions, the decrease in available β1-AR concentration shifts both NE− and NE+ β-nullclines to the left (compare B and D), while the inhibition of GRK2 shifts the NE+ β-nullcline to the right, closer to the NE- β nullcline." (PMID 33740423, 2021). "Notably, the severity of RKIP-induced symptoms of heart failure could be a consequence of the dual activity of RKIP as GRK2 and Raf1-Erk1/2 axis inhibitor." (PMID 30687708, 2018). "Besides the contribution to myocardial hypertrophy, PI3K also induces internalization and downregulation of β-adrenoceptors via the interaction with GRK2, which may promote the heart failure." (PMID 30150938, 2018). "In a porcine model of heart failure following left ventricular (LV) myocardial infarction, AAV6-mediated delivery of βARKct, (a GRK2 inhibitor peptide) improved left ventricular hemodynamics and contractility." (PMID 41179895, 2025). "The most well-studied GRKs are GRK2 and GRK5, two important therapeutic targets, as their inhibition can prevent heart failure and hypertrophic cardiomyopathy." (PMID 40040803, 2025).
heart failure (continued). "SD increases AF susceptibility by modulating the autonomic nervous system toward sympathetic predominance, resulting in heart failure with SAN dysfunction, suppressed GRK2 expression, and enhanced PV and LA arrhythmogenesis." (PMID 39062858, 2024). "Heart failure is an adult disease, and we assessed the short-term effects by overexpressing GRK2 in adulthood using AAV for GRK2 overexpression." (PMID 37173348, 2023). "While GRK2 is upregulated, several studies documented that the β1-adrenoceptor (ADRB1) is downregulated in human heart failure." (PMID 35203304, 2022). "Heart failure-promoting activities of RKIP involve the dual functions of RKIP as a RAF1 inhibitor and GRK2 inhibitor." (PMID 35203304, 2022). "Our results suggest a mechanistic justification for this hypothesis: lowering GRK2 activity alongside β1-AR inhibition reduces the amplitude of cAMP overshoot, and partially rescues the dynamic range of cAMP concentration compared with β-blockers alone in heart failure conditions." (PMID 33740423, 2021). "Overall, results presented here show the role of RH domain of GRK2 in the desensitization of β3AR, a GPCR that has been proposed as a therapeutic target for long term treatment of heart failure." (PMID 32153413, 2020). "BetaARK1 (also known as GRK2) is the most abundant GRK in the heart, and it is increased in several cardiovascular diseases associated with impaired cardiac signaling and function, suggesting that this protein could have pathophysiological relevance in the setting of heart failure." (PMID 20204079, 2009). "The phosphorylation of β2ARs by GRK-2 and PKA in the desensitization process favors receptor coupling to Gαi/o proteins as a protective mechanism in heart failure, and the decrease in β-arrestin 1 could reduce β2AR desensitization as a counteracting mechanism." (PMID 40869310, 2025). "Comparison between C and E can be thought of as the scenario in which GRK2 activity increases in early heart failure, and β-blockers do not reduce this upregulation." (PMID 33740423, 2021). "To date, the impact of a GRK2 inhibitor on human therapy cannot be foreseen despite the evidence that short peptides derived from the HJ loop of GRK2 possess promising metabolic effects in animal models of Type 2 diabetes and IRES, as well as in endothelial function and heart failure." (PMID 33467677, 2021). "Because the PKC-activating DAG was strongly increased in Tg-RKIP hearts, we investigated whether RKIP acted as GRK2 inhibitor in vivo, in Tg-RKIP mice with signs of heart failure." (PMID 30687708, 2018). "In contrast to Tg-RKIP hearts, transgenic expression of GRK2-K220R did not up-regulate any of these heart failure-promoting genes." (PMID 30687708, 2018). "In contrast to cardioprotective GRK2 inhibition with kinase-inactive GRK2-K220R, transgenic expression of the dual-specific GRK2 and Raf-Erk1/2 axis inhibitor, RKIP, promoted signs of heart failure, i.e., cardiac hypertrophy, cardiac dilatation and cardiotoxic lipid load." (PMID 30687708, 2018). "Here, GRK2 expression has been reported to be inhibited in animals with cardiac hypertrophy without heart failure, whereas animals with heart failure had elevated GRK2." (PMID 20204079, 2009). "Interestingly, our study found that despite chronic sympathetic overactivity and overt heart failure in SD rats, the SD LA did not exhibit compensatory overexpression of GRK2 along with β1-ARs downregulation." (PMID 39062858, 2024). "Interestingly, GRK2 hemizygous animals also show an increased activation of AMPK, an activator of mitochondrial fatty acid oxidation and of PGC-1α expression, also suggested to play a protective role in heart failure." (PMID 27832814, 2016). "Interestingly, GRK2 directly phosphorylates IRIS in cardiomyocytes, a process that negatively affects cardiac glucose uptake and insulin sensitivity following ischemic injury and ultimately leads to the development of heart failure." (PMID 24265619, 2013).